TSLP (thymic stromal lymphopoietin)
Diseases named in the same sentence as TSLP in open-access papers (continued):
Sharing a sentence is not in itself a finding about the gene and the disease.
tumor (continued). "Collectively, in the majority of studies through Th2-independent mechanisms, TSLP exerted pro-tumor activity (i.e., breast, lung, cervical, and blood cancers)." (PMID 33042121, 2020). "The Th2-mediated immune response had long been recognized as a favorable factor for tumor proliferation by promoting fibroblast thymic stromal lymphopoietin production, angiogenesis, and by suppressing the cell-mediated immune response." (PMID 32733914, 2020). "TSLP expression in the tumor was significantly higher than in the surrounding tissue, and it was supported by CAFs activated by tumor-derived cytokines." (PMID 33042121, 2020). "This distinction is mostly based on the association between TSLP expression and the development of predominant Th2 inflammation in the tumor or direct TSLP signaling on TSLPR expressing tumor cells." (PMID 33042121, 2020). "Studies focusing on tumors of hematopoietic and lymphoid tissues such as lymphoma and acute lymphocytic leukemia (ALL) reported TSLP as a tumor-progressive factor." (PMID 32849527, 2020). "The induction and accumulation of Th2 cells in the tumor microenvironment were driven by thymic stromal lymphopoietin (TSLP)-activated myeloid dendritic cells (DCs) expressing the receptor for TSLP." (PMID 33022971, 2020). "We previously reported that in PDAC predominant Th2 cells correlated with TSLP expression by CAFs and tumor infiltration by TSLP receptor-expressing DCs, pointing to TSLP as a master regulator of pro-tumor Th2 inflammation in PDAC." (PMID 30760333, 2019). "Recently, many works have suggested that TSLP can play a key role in the BC tumor microenvironment and influence BC progression." (PMID 31210014, 2019). "We found that Th2 inflammation depends on a complex crosstalk within the tumor microenvironment and tumor-draining lymph nodes with a central role exerted by the thymic stromal lymphopoietin (TSLP)." (PMID 30760333, 2019). "To probe into the molecular mechanism that YPFS inhibited the tumor angiogenesis through affecting the activation of TSLP, we examined the expression of TSLP/TSLPR and STAT3/p-STAT3 under the treatment of the anti-TSLP antibody and YPFS in vivo and in vitro." (PMID 31885639, 2019). "An HMGB1-TSLP (thymic stromal lymphopoietin) axis has been demonstrated, where tumor-derived HMGB1 and TSLP enhance DC-mediated activation of Tregs, a phenomenon that was dependent on the presence of the TSLP receptor on DCs." (PMID 31379812, 2019). "TSLP is now considered to have multiple effects on different immune cells including T cells, B cells, and dendritic cells, which are involved in tumor initiation, growth, angiogenesis, metastasis, and tumor immunity." (PMID 31023965, 2019). "Altogether, these results of the present study suggested that the anti-angiogenesis effect of YPFS participates in its suppression of tumor growth through the TSLP/STAT3 signaling pathway." (PMID 31885639, 2019). "Here we show that IL-1α and IL-1β derived from tumor cells and tumor cell-conditioned macrophages is key for TSLP production by CAFs and blockade of IL-1 in vivo significantly reduced TSLP expression in the tumor." (PMID 30760333, 2019). "We found the expression of TSLP/TSLPR and STAT3/p-STAT3 in tumor tissues treated with the anti-TSLP antibody was significantly decreased compared with the vehicle group." (PMID 31885639, 2019). "Taking these papers into account, we suggest that TSLP should be considered the key player in promoting cancer development through the immune response in the tumor itself." (PMID 31210014, 2019). "In the present study, we report that tumor-derived IL-1α and IL-1β exert a primary role in driving TSLP secretion by CAF and that in vivo treatment with anakinra significantly reduces TSLP expression in the tumor." (PMID 30760333, 2019). "TSLP secretion by CAFs was used as a read-out system to identify in vitro relevant tumor-derived inflammatory cytokines and molecules." (PMID 30760333, 2019).
tumor (continued). "TSLP then enhances tumor cell survival by inducing the expression of the anti-apoptotic protein Bcl2." (PMID 31366131, 2019). "In this study we identified IL-1 derived by tumor cells and TAMs as relevant inducers of TSLP release by CAFs (in red)." (PMID 30760333, 2019). "Based on the cross-talk between Th2 inflammation and cancers, a recent study shows that tumor progression is promoted by Th2-differentiated CD4+ T cells in response to TSLP." (PMID 31885639, 2019). "The present study demonstrated that, in addition to CAFs, PDAC cells directly produce TSLP in vivo, suggesting further immune-response manipulation in promoting tumor growth in the tumor itself." (PMID 30214685, 2018). "Tumor-produced TSLP has been shown to up-regulate OX40L expression on DCs, thus inducing the generation of Th2 cells that produce IL-4 and IL-13 that have been shown to promote tumor growth in breast and pancreatic cancer." (PMID 30619378, 2018). "Thymic stromal lymphopoietin (TSLP), produced by activated CAFs, is capable of activating myeloid DCs to acquire Th2-polarizing capability in the tumor microenvironment." (PMID 29915688, 2018). "This explorative study found that PDAC cells themselves, both in vitro and in situ, can elaborate TSLP, a cytokine known to promote type 2 activation/maturation of resident tumor DCs." (PMID 30214685, 2018). "Abnormally elevated TSLP levels were detected in situ in tumor cells and, systemically, in locally-advanced/metastatic PDAC patients." (PMID 30214685, 2018). "In contrast to these studies, two groups have demonstrated a tumor-suppressing role for TSLP in murine models of skin carcinoma." (PMID 30057581, 2018). "Additional studies will be required to reveal the mechanistic basis of the tumor-promoting vs. tumor-suppressive effects of TSLP in different cancers, before TSLP can be recognized as a potential target for therapeutic intervention." (PMID 30214685, 2018). "An increasing number of studies have focused on the complicated role of TSLP in several cancers: it is tumor-promoting in some instances, and tumor-inhibiting in others." (PMID 30214685, 2018). "Recent studies in humans show that TSLP, being expressed in the tumor microenvironment, plays a role in promoting a Th2-like environment in the tumor." (PMID 30214685, 2018). "TSLP can induce immunological memory leading to the atopic march, and has proven potential in inducing anti-tumor immunity in mice and man." (PMID 28953906, 2017). "A question raised by this study is how IL-31 and TSLP can modulate the HL lymph node microenvironment to support tumor growth." (PMID 29156718, 2017). "The TSLP/TSLPR axis has been shown to promote tumor cell survival in both solid tumors and leukemia." (PMID 29156718, 2017). "We compared TSLP expression in tumor and macroscopically uninvolved surrounding tissues from surgical specimens at both mRNA and protein levels by qRT-PCR and ELISA assay of tissue homogenates, respectively." (PMID 26919238, 2016). "The pro-tumor role of TSLP in those studies has been attributed to its ability to promote the inflammatory Th2 microenvironment." (PMID 26919238, 2016). "There were significant decreases in the volume and the weight of tumors from TSLP-treated group compared with those from control mice, indicating the inhibitory effect of TSLP on tumor growth." (PMID 26919238, 2016). "There were much more TUNEL-staining apoptotic cells in the tumor sections from TSLP-treated mice than those from control mice." (PMID 26919238, 2016). "In contrast, a much lesser extent of TSLP-positive staining was detected in the tumor tissues, which was consistent with the results of ELISA assay." (PMID 26919238, 2016). "For example, LC induce Treg during L. major and Th17 cells upon C. albicans infection, Th2 cells under the influence of pro-allergic TSLP and strong Th1 responses when conditioned by a tumor environment." (PMID 26557117, 2015).
tumor (continued). "On the contrary TSLP has convincingly been shown in mouse in vivo models to be critically important for resistance to skin carcinogenesis establishing TSLP as a tumor suppressor in the skin." (PMID 25101088, 2014). "OX40L is upregulated by thymic stromal lymphopoietin (TSLP), which is expressed by cancer cells in the tumor environment." (PMID 21281484, 2011). "The distinct effects of TSLP observed in the two studies may reflect that baseline TSLP engages an innate immune axis in the tumor, while TSLP induction by calcipotriol treatment leads to robust antitumor adaptive immunity." (PMID 39782693, 2025). "Th2-polarized CD4+ T cells responding to TSLP played a seminal role in tumor suppression in vivo." (PMID 39744942, 2025). "TSLP has been found to either promote tumor destruction or tumor growth." (PMID 39744952, 2025). "Similarly, high-dose TSLP (100–200 ng/mL) induces apoptosis in colon cancer cells in vitro and reduces tumor size when injected peritumorally." (PMID 40787610, 2025). "CD4+ T cells are responsible for TSLP-mediated tumor protection in the skin." (PMID 39744942, 2025). "This TSLP activates and matures resident DCs loaded with tumor antigens." (PMID 40453074, 2025). "TSLP-mediated tumor protection was mediated by CD8+ and CD4+ T cells." (PMID 40873585, 2025). "Th2 polarization is required for TSLP-mediated tumor protection." (PMID 39744942, 2025). "We observed that GBM tumor cells of U251 or GBM-b express TSLP when stimulated with EGF." (PMID 41516199, 2025). "In addition, the role of TSLP as an inhibitor of apoptosis has been proposed in both immune and tumor cells." (PMID 38557942, 2024). "However, when PMNs were co-cultured with tumor cells, TSLP promoted a significantly higher survival rate, demonstrating an antiapoptotic role." (PMID 38557942, 2024). "Additional studies are warranted to delve deeper into the specific mechanisms through which TGF-β3, TSLP, and possibly other tumor-derived factors may contribute to myeloid cell education and elevated IL-6 and OSM expression." (PMID 38236642, 2024). "Moreover, the expression of TSLP by myeloid cells (neutrophils and monocytes), induced by tumor-derived IL-1α, favored tumor cells survival." (PMID 38557942, 2024). "Moreover, the expression of TSLP and its receptor has been demonstrated in different solid tumors, where it provides a potential mechanism of escape from anti-tumor immunity by polarizing immunity towards a Th2 TME." (PMID 38398754, 2024). "Xie and colleagues investigated the correlation between TSLP and tumor growth in vitro." (PMID 37587450, 2023). "TSLP also affects CRC progression by regulating the function of tumor-specific regulatory T cells." (PMID 38025525, 2023). "In order to do this, different mechanisms have been proposed: tumour growth can be caused through eosinophil-derived CCL22, by thymic stromal lymphopoietin (TSLP) that induces angiogenesis via VEGFA and by eosinophils-derived epidermal growth factor (EGF) along with TGF-β." (PMID 35406451, 2022). "TSLP signals through TSLPR expressed by DCs to exert its promoting effect on B16F10 tumour growth." (PMID 36107619, 2022). "In a more recent report, this progrowth function of TSLP was linked to a tumor-myeloid cell axis that is independent of T cell responses." (PMID 35657353, 2022). "Although TSLP’s effect on suppressing tumor initiation in the lung was marginal (reflected in the number of tumor foci developed in the lung), we found TSLP induction to strongly suppress lung tumor promotion reflected in average tumor size and percentage of the lung surface area covered by tumors." (PMID 35565302, 2022). "Thus, TSLP appears to play a dual role, providing both pro and antitumor immunity depending on its expression level and the tumor context." (PMID 36467403, 2022).
tumor (continued). "Considering a significant reduction in tumor cell proliferation in Tslptg KrasG12D tumors compared with KrasG12D tumors, cytotoxicity is unlikely to be the main mode of antitumor immunity downstream of TSLP induction in the lung." (PMID 35565302, 2022). "Immunosuppression was observed by eosinophils-derived indoleamine 2,3-dioxygenase (IDO) (inhibition of effector T cells) and by an increasing of IL-4 and IL-13-expression by eosinophils via TSLP leading to conversion of macrophages into tumour-promoting activation state." (PMID 35406451, 2022). "The in vivo exposure to tumor microenvironment may have affected the expression of TSLP system and the functional activity of lung macrophages." (PMID 34440780, 2021). "Also in MM, malignant B cells have been shown to induce MSCs to secrete pro-tumor cytokines, as well thymic stromal lymphopoietin (TSLP) that activated TH2-type inflammation in the BM TME resulting in tumor progression." (PMID 33842331, 2021). "BC cell-derived IL-1α also induces expression of TSLP from tumor infiltrating myeloid cells, and TSLP, in turn, induces expression of B cell lymphoma-2 (Bcl-2) in tumor cells, promotes tumor cell survival, and skews the TME toward Th2 inflammation, sustaining lung metastatic survival." (PMID 34602858, 2021). "A pro-tumor activity for TSLP was described in gastric and ovarian cancer patients where TSLP overexpression in tumor compared to normal tissue correlated with LN metastases, and TSLP expression was identified as an independent predictive factor of reduced survival." (PMID 33042121, 2020). "TSLP expression and pro-tumor or anti-tumor function in human and mouse cancers." (PMID 33042121, 2020). "Thus, TSLP overexpression and its pathways play an important role in inducing Th2-immunosuppressive state in tumor microenvironment." (PMID 32351590, 2020). "Consequently, the expression of GM-CSF, TSLP, phosphorylated STAT3, β-catenin, and cyclin D1 in the transplanted tumors was evaluated using Western blotting, and the expression of GM-CSF, TSLP, β-catenin and cyclin D1 was examined in tumor sections." (PMID 32887217, 2020). "Collectively, in the majority of studies TSLP and Th2 inflammation exerted pro-tumor activity." (PMID 33042121, 2020). "Surprisingly, we found that YPF could significantly reduce the TSLP expression and restore Th1/Th2 balance in tumor and adjacent tissues." (PMID 32351590, 2020). "In CTCL, fibroblast-derived periostin mediated TSLP production by keratinocytes that in turn directly stimulated in vitro tumor cell growth in TSLPR-expressing tumor cells, and in vivo TSLP inhibition reduced tumor formation in EL-4 and MBL-2 cell mouse models." (PMID 33042121, 2020). "We present the first evidence of TSLP protein expression in tumor and adjacent tissues of HCC." (PMID 32351590, 2020). "Results from diverse experimental and clinical studies in diverse solid tumors—cervical, ovarian, pancreatic, or gastric cancer further imply an evident tumor-progressive role of TSLP in tumor microenvironment leading to the promotion of tumor angiogenesis and its growth and metastasis." (PMID 32849527, 2020). "It has been recently shown that some human tumor cells from PDAC can produce TSLP leading to increased survival and activation of ILC2s/IL-5/Eosinophil axis which in turn could impair tumor growth by a similar mechanism." (PMID 33233582, 2020). "In contrast, another study proposed its pro-tumor role with the evidence that the keratinocyte-specific overexpression of TSLP (in K14-TSLP transgenic mice) could inhibit the development of early BRCA." (PMID 33193571, 2020). "In both models CD4+ Th2 cells were shown to mediate the tumor-suppressive effects of TSLP." (PMID 33042121, 2020). "Indeed, in vitro studies showed that ASC released by tumor cells induced IL-1β release by macrophages, and CAFs, activated with the supernatant of ASC positive tumor cell-conditioned macrophages, secreted TSLP." (PMID 32117971, 2020).
tumor (continued). "CAFs respond to tumor-derived TNFα and IL-1β to secrete thymic stromal lymphopoietin (TSLP)." (PMID 31143179, 2019). "As a member of the IL-2 cytokine family and a distant paralog of IL-7, oncogene properties of TSLP, such as pro-tumorigenic, cancer cell protective, and tumor growth promoting properties, have been reported in various animal models of cancers, as well as in studies conducted on humans." (PMID 31023965, 2019). "Furthermore, HMGB1-mediated production of thymic stromal lymphopoietin (TSLP) by tumor cells can modulate DCs via the TSLP receptor under physiological conditions." (PMID 31307548, 2019). "Finally, we assessed the relevance of tumor cell-derived ASC in the induction of TSLP secretion by CAFs." (PMID 30760333, 2019). "Taken together, the present study confirmed that YPFS inhibited angiogenesis and tumor growth in mice bearing HCC, which may be associated with the attenuation of the TSLP/STAT3 signaling pathway." (PMID 31885639, 2019). "Meanwhile, we also found YPFS could significantly reduce the expression of the TSLP in tumor and adjacent tissues." (PMID 31885639, 2019). "Collectively, the data suggest that extracellular ASC released by tumor cells induces IL-1β secretion in TAMs that in turn activates TSLP by CAFs and that ASC is expressed in a high percentage of primary tumors where its expression correlates with reduced survival in PDAC patients." (PMID 30760333, 2019). "In summary, we identified tumor-derived IL-1α and IL-1β as key cytokines in driving TSLP secretion by CAFs and tumor-released ASC, whose expression in PDAC correlates with reduced patients’ survival, as a relevant component in the inflammatory cascade involving activation of IL-1β secretion by TAMs." (PMID 30760333, 2019). "Many previous research studies support this hypothesis, reporting the key role of TSLP in promoting a tumor microenvironment through the Th‐2 cytokines expression." (PMID 31210014, 2019). "However, TSLP’s emerging ambiguous role in tumor immunology complicates the decision over how to manipulate TSLP, or its signaling pathway, in managing cancer patients." (PMID 30214685, 2018). "Finally, using a xenograft mouse model, the authors found that peritumoral administration of TSLP reduced tumor growth." (PMID 30057581, 2018). "The results of this study are consistent with the notion that local and systemic tumor-derived TSLP may, with other concomitant immune-suppressive cytokine pathways, contribute to limiting the anti-tumor therapeutic responses to DC-based vaccines in PDAC." (PMID 30214685, 2018). "In certain neoplasias, TSLP plays a pro-tumorigenic role, whereas in others, a protective role." (PMID 30057581, 2018). "It is thus tempting to hypothesize that, in early-stage PDAC, the prevalence of the short TSLP isoform, predominantly produced by cells that are still well/moderately-differentiated, may control tumor growth." (PMID 30214685, 2018). "Finally, using a xenograft mouse model, we demonstrated that peritumoral administration of TSLP greatly reduced tumor growth accompanied with extensive tumor apoptotic response, which was abolished by tumor cell-specific knockdown of TSLPR." (PMID 26919238, 2016). "This indicates that when tumours do arise in an atopic environment, TSLP may have a tumour growth-promoting role." (PMID 24843010, 2014). "TSLP has potent anti-tumour activity in skin carcinogenesis." (PMID 24843010, 2014). "TSLP may have an important role in tumor progression by activating CD4+ T cells, inducing the expressing of OX40L in dendritic cells (DCs), and producing Th2-type cytokines and B-cell growth factor." (PMID 25075970, 2014). "Moreover, the combination of TSLP with neutrophil infiltration is associated with worse patient prognosis and survival, suggesting that GBM may contribute to immunomodulation of the tumor microenvironment through the production of TSLP, as previously reported." (PMID 41516199, 2025).